NEFM (neurofilament medium chain)
Description:
Neurofilaments usually contain three intermediate filament proteins: NEFL, NEFM, and NEFH which are involved in the maintenance of neuronal caliber. May additionally cooperate with the neuronal intermediate filament proteins PRPH and INA to form neuronal filamentous networks (By similarity).
Synonyms: NF-M; NEF3; NFM
Tractability: PROTAC: ubiquitination databases record sites on it; its protein half-life has been measured.
Gene: Protein-coding gene on chromosome 8 (24,913,758 to 24,919,098, forward strand). Ensembl gene ENSG00000104722.
Subcellular location: Cytoplasm, cytoskeleton; Cell projection, axon; Perikaryon
Subcellular location (Human Protein Atlas): Intermediate filaments
Gene Ontology:
Molecular function: protein binding; microtubule binding; structural constituent of cytoskeleton; structural molecule activity
Biological process: neurofilament bundle assembly
Cellular component: intermediate filament cytoskeleton; neurofibrillary tangle; perikaryon; axon; intermediate filament; neurofilament; postsynaptic intermediate filament cytoskeleton; cytoskeleton
Genetic constraint (gnomAD): Loss-of-function variants: 18 observed, 49.29 expected, observed/expected ratio (o/e) 0.37, 90% interval 0.25 to 0.54. The upper end of that interval is the gene's LOEUF score, 0.54, which puts it in group 2 of 6, group 1 being the genes least tolerant of losing a copy. Missense variants: 1,106 observed, 1,185.5 expected, observed/expected ratio (o/e) 0.93, 90% interval 0.89 to 0.98. Synonymous variants: 463 observed, 473.93 expected, observed/expected ratio (o/e) 0.98, 90% interval 0.9 to 1.05.
Homologues: Orthologues: chimpanzee NEFM (98% identical), macaque NEFM (97% identical), rat Nefm (82% identical), dog NEFH (36% identical). Paralogues in human: NEFL (27% identical), INA (26% identical), PRPH (22% identical), VIM (21% identical), DES (20% identical), GFAP (20% identical), NES (16% identical), KRT75 (16% identical), KRT8 (16% identical), KRT6A (15% identical), KRT5 (15% identical), KRT6B (15% identical), and 56 more.
Diseases named in the same sentence as NEFM in open-access papers:
NEFM is named in the same sentence as 87 diseases in open-access papers, as found by Europe PMC text mining. Sharing a sentence is not in itself a finding about the gene and the disease. The quoted sentences say what the papers report.
Alzheimer disease (6 papers, 2016 to 2025). A progressive, neurodegenerative disease characterized by loss of function and death of nerve cells in several areas of the brain leading to loss of cognitive function such as memory and language. "The possibility of increased protein synthesis has been ruled out in degenerating neurons of ALS and Alzheimer disease patients in which NEFL mRNA levels are downregulated, whereas the transcript levels for NEFM or NEFH usually remain unchanged." (PMID 27021905, 2016).
glioma (5 papers, 2008 to 2022). A benign or malignant brain and spinal cord tumor that arises from glial cells (astrocytes, oligodendrocytes, ependymal cells). "This interaction enhances the levels of neurofilament medium (NEFM), a tumor suppressor in glioma, resulting in decreased cell proliferation." (PMID 35535385, 2022). "More importantly, NEFM, a tumor suppressor, was reported to be significantly reduced in cancerous conditions and boost in glioma cells through LINC00294 up-regulation." (PMID 34861891, 2021). "For example, among the neurofilament genes (INA, NEFH, NEFM, NEFL) present in cluster C, alphainternexin (INA) was the only one overexpressed in both gliomas with 1p19q codeletion and cortex samples in comparison to gliomas with EGFR amplification." (PMID 18492260, 2008).
neuroblastoma (5 papers, 2012 to 2022). Neuroblastoma (NB) is the most common solid, extracranial childhood tumor. "Analysis of genes that are increased with retinoic acid induced differentiation of neuroblastoma cells (NGRF, NF68, NTRK1, SYP, MAP2, NEFM, DKK2) showed that all were elevated after 72 hours Wnt3a/Rspo2 treatment." (PMID 29505958, 2018). "A precise role for NEFM during neuroblastoma progression, invasion or metastasis has not yet been described." (PMID 30228356, 2018). "In addition, immunoblot analysis revealed that overexpression of KDM6B, but not its mutant, increased NEFM protein levels in neuroblastoma cells." (PMID 30631055, 2019).
breast carcinoma (4 papers, 2019 to 2025). "However, NEFM DNA methylation was significantly negatively associated with immune infiltration in breast cancer." (PMID 34001208, 2021). "Silencing or low expression of NEFM correlated with breast cancer progression, immune cell infiltration, and poor survival." (PMID 40563693, 2025). "Since the different results from correlation analysis and TISIDB databases, TIMER gene modules were applied to evaluate the relationship of NEFM transcriptional expression with immune infiltration in breast cancer." (PMID 34001208, 2021). "Relationship of NEFM transcriptional expression/DNA methylation with immune infiltration in breast cancer was assessed using correlation analysis and TISIDB databases." (PMID 34001208, 2021). "In this study, NEFM transcriptional expression was downregulated and negatively correlated with DNA methylation in breast cancer." (PMID 34001208, 2021). "In breast cancer, we infer that NEFM transcriptional expression may affect survival partially through the decreased M2 macrophage infiltration and anti-tumor cytotoxicity of cytokine–cytokine receptor interaction and IL-17 signaling pathway." (PMID 34001208, 2021). "Therefore, our study highlights potential clinical significance of NEFM transcriptional expression/DNA methylation in breast cancer and provides insight into a novel role of NEFM expression/DNA methylation in tumor immune infiltration." (PMID 34001208, 2021). "However, whether NEFM is involved in regulating antitumor immunity with clinical significance in breast cancer remains unknown." (PMID 34001208, 2021).
Parkinson disease (4 papers, 2009 to 2024). A progressive degenerative disorder of the central nervous system characterized by loss of dopamine producing neurons in the substantia nigra and the presence of Lewy bodies in the substantia nigra and locus coeruleus. "We quantified methylation of 2 identified regions at adjacent genes (HCN2 and NEFM) known to increase the risk for Parkinson’s disease and observed significant hypomethylation." (PMID 32178731, 2020). "The lack of repressive signaling from CTCF could contribute to the observed increases in NEFM reported in Parkinson’s disease patients and the observed overexpression of NEFM associated with cytoplasmic inclusions in motor-impaired mice." (PMID 32178731, 2020). "Both HCN2 and NEFM are regionally expressed in Parkinson’s disease tissues and their function has a critical role in neuronal plasticity and survival detailed in “Discussion” section." (PMID 32178731, 2020).
lung carcinoma (3 papers, 2016 to 2021). "NEFM is a nuclear export mediator that have been implicated as a tumor suppressor in lung cancer." (PMID 26818387, 2016). "The upregulated genes included CYP4F3, IL1RL1, PTGS2, and CXCL8, which are related to inflammation; HKDC1, MYEF2 and CYP1A1, which are related to hepatocarcinoma or lung carcinoma; and SLC7A11 and NEFM, which are related to neuronal damage." (PMID 33247188, 2020).
thymoma (3 papers, 2022 to 2025). A neoplasm arising from the epithelial cells of the thymus. "Interestingly, the NEFM (Neurofilament Medium Chain) gene coding for a neuronal protein NEFM was found to be highly expressed (30-fold and >100-fold) in MG-associated thymoma cases." (PMID 40416967, 2025). "NEFM epitopes were previously found to be expressed in thymoma TECs." (PMID 36979710, 2023). "Our real-time PCR analyses showed an NEFM overexpression in both MG and non-MG thymomas compared to follicular hyperplastic MG and normal control thymuses." (PMID 36979710, 2023). "The NEFM expression levels were significantly higher in the MG A/AB subset compared to the same subset in the non-MG thymoma group, which is in line with Radovich’s findings." (PMID 36979710, 2023). "However, by stratifying the tumors according to the WHO type, we identified a significant NEFM mRNA level increase in type A/AB MG thymomas compared to the corresponding subset in the non-MG thymoma group." (PMID 36979710, 2023). "However, since NEFM overexpression was not exclusive to MG thymomas, we think that it may be a histopathological feature of the thymic neoplastic microenvironment that is potentially able to predispose, but not sufficiently, anti-AChR autoimmunity." (PMID 36979710, 2023). "Among the genes encoding muscle-like autoantigens, NEFM and RYR3 had a more similar gene expression pattern and were clustered together in one group; they were both particularly overexpressed in type A/AB MG thymomas compared to the same tumor type in the non-MG thymoma group." (PMID 36979710, 2023). "We thus assessed the NEFM, RYR3, and HSP60 expression in hyperplastic and thymoma MG thymuses, non-MG thymomas, and normal thymuses, using real-time PCR." (PMID 36979710, 2023). "The autoantibody titer did not correlate with the expression levels of CHRNA1, NEFM, and HSP60 in follicular hyperplastic and thymoma MG thymuses." (PMID 36979710, 2023). "Microarrays data from Radovich and colleagues demonstrated that the transcriptional levels of the medium-sized neurofilament, NEFM, which exhibit immunogenic similarities with AChR-α and TTN, were higher in MG compared to non-MG thymomas, and even higher in the MG A/AB subset." (PMID 36979710, 2023).
adenoma (2 papers, 2016 to 2020). A neoplasm arising from the epithelium. "NEFM was also down-regulated in ZF-like aldosterone-producing adenomas and contributed to a D1R/D2R imbalance." (PMID 33324198, 2020). "We identified hypermethylated CpG sites in the following genes: L3MBTL1, NKX6-2, PREX1, TRAF7, PRDM14, and NEFM with the number of CpG sites being 14, 17, 10, 16, 6, and 6, respectively, after pairwise analysis of normal versus adenoma, adenoma versus cancer, and normal versus cancer." (PMID 27688749, 2016).
cognitive decline (2 papers, 2024 to 2025). "Seven of the 22 peptides associated with the frail vs control diagnostic contrast and cognitive decline were cytoskeleton-related, including proteoforms of MAP2, VIM, TUBB, DBN1, TUBA8, PALM and NEFM." (PMID 38531951, 2024).
depression (2 papers, 2012 to 2022). "ACTB, CKB, NEFL, INA and GFAP had link to both schizophrenia and depression, while CTSD, HSPA8, NEFM and TUBA1A had link to schizophrenia." (PMID 23272063, 2012).
sarcoma (2 papers, 2018 to 2021). A usually aggressive malignant neoplasm of the soft tissue or bone. "In addition, fused in sarcoma/translocated in liposarcoma (FUS/TLS), another ALS-associated protein, has been shown to bind to murine NEFL, NEFM and NEFH transcripts." (PMID 30029677, 2018).
adenomyosis (1 paper, 2022). The growth of endometrial tissue inside the muscular wall of the uterine corpus. "We also did qPCR on the adenomyosis pain group and the non-pain group and discovered that several mRNAs associated with nerve growth and neuroinflammatory factors, NEFM, GATA2, HMGA1, and IGFBP6, were considerably more strongly expressed in the adenomyosis pain group than in the non-pain group." (PMID 36532077, 2022).
astrocytoma (1 paper, 2013). "NEFM encodes the medium neurofilament protein and has been reported previously to be methylated in pancreatic cancers and astrocytoma." (PMID 24034811, 2013).
breast tumors (1 paper, 2021). "It was reported that methylation-mediated inactivation of NEFH, NEFL or NEFM was common in primary breast tumors compared to normal breast tissues and correlated with clinical features of disease progression." (PMID 34001208, 2021). "Integrated analysis confirmed the inverse relationship of NEFM DNA methylation in Illumina Infinium HumanMethylation450 array with NEFM transcriptional expression in TCGA breast tumors." (PMID 34001208, 2021).
epilepsy (1 paper, 2023). A brain disorder characterized by episodes of abnormally increased neuronal discharge resulting in transient episodes of sensory or motor neurological dysfunction, or psychic dysfunction. "ADGRG1, LGI3 and NEFM are known to play roles in neural development and are associated with neurological diseases, such as epilepsy." (PMID 37185447, 2023).
glaucoma (1 paper, 2023). Increased pressure in the eyeball due to obstruction of the outflow of aqueous humor. "We identified multiple genes of interest with higher relative expression in glaucoma-related cell types; examples include NEFM, SYT2 expression in RGCs, AQP5 and KRT3 expression in corneal epithelial cells and CDH6 in ciliary muscle." (PMID 36833422, 2023).
neurofibroma (1 paper, 2012). An intraneural or extraneural neoplasm arising from nerve tissues and neural sheaths. "Previous studies have reported the mRNA expression of NEFM and tubulin in SCs and TUBB3 expression in neurofibroma SCs." (PMID 22443529, 2012).
oligodendroglioma (1 paper, 2020). A well-differentiated (WHO grade II), diffusely infiltrating neuroglial tumor, typically located in the cerebral hemispheres. "In our cohort, tumors expressing canonical neuronal markers like neurofilament (NEFL, NEFM, and NEFH) and synaptophysin (SYP) were significantly localized within the expression space of oligodendrogliomas (q-value < 0.015)." (PMID 32732999, 2020).
prostate carcinoma (1 paper, 2020). A carcinoma that arises from epithelial cells of the prostate gland. "Finally, it has been demonstrated that NEFM was diffusely expressed in prostate cancer cells undergoing neuronal trans-differentiation and NOL4 was described as a biomarker for aggressiveness prostate cancer." (PMID 32041153, 2020).
renal carcinoma (1 paper, 2016). A carcinoma arising from the epithelium of the renal parenchyma or the renal pelvis. "The impact of the hypermethylated NEFM gene has been reported in renal cancer, and it is consistent with our results that this gene plays an important role in colorectal carcinogenesis." (PMID 27688749, 2016).
renal cell carcinoma (1 paper, 2016). "NEFM is a gene located in chromosome 8p and is hypermethylated in renal cell carcinoma." (PMID 27688749, 2016).
small cell lung carcinoma (1 paper, 2014). Small cell lung cancer (SCLC) is a highly aggressive malignant neoplasm, accounting for 10-15% of lung cancer cases, characterized byrapid growth, and early metastasis. "Along with KRT20, NEFM was shown to be effective at discriminating MCC from small cell lung carcinoma with the majority of MCC being positive for both NEFM and KRT20 while NEFM and KRT20 were almost completely absent from small cell lung carcinoma." (PMID 24634783, 2014).
tubular adenoma (1 paper, 2016). A usually polypoid neoplasm arising from the glandular epithelium. "The last identified marker in this study is NEFM (NM_005382) where 12 methylated CpG sites were identified within the gene's promotor region in tumor samples, while no CpG sites were found to be methylated in normal, tubular adenoma, and tubulovillous adenoma samples." (PMID 27688749, 2016).
cancer (11 papers, 2010 to 2025). A tumor composed of atypical neoplastic, often pleomorphic cells that invade other tissues. "Neurofilaments have been implicated in the pathology of cancers, and NEFM is located in Ch8p21, where loss of heterozygosity has been shown in several cancers." (PMID 40563693, 2025). "Association of NEFM transcriptional expression/DNA methylation with cancer immune infiltration was investigated using TIMER and TISIDB databases." (PMID 34001208, 2021). "Consistently, we demonstrated that NEFM transcriptional expression was downregulated in most cancers including breast, colorectal, gastric, kidney, head and neck, compared with normal tissues in Oncomine and TIMER databases." (PMID 34001208, 2021). "Potential impact of NEFM expression on overall survival (OS) was evaluated in Pan-cancer RNA-seq in Kaplan–Meier plotter." (PMID 34001208, 2021). "DNA methylation-mediated inactivation of NEFH, NEFL and NEFM also occur in other types of cancer originated from pancreas, gastric and colon." (PMID 34001208, 2021). "Cells in cluster 5 resembled those in cluster 7 of DNs, and included cells with aberrant neuronal identity that expressed neuronal genes (GAP43, NEFM, DCX, HES6) and cancer-related proliferative genes (CRABP1, MYC, SFRP1)." (PMID 33771987, 2021). "Cluster 7 included cells with aberrant neuronal identity that expressed neuronal development genes (NEFM, DCX, STMN2, HES6) but also cell cycle and cancer-related genes (CRABP2, CCND1, MYC)." (PMID 33771987, 2021). "NEFL and NEFM are located within 8p21, and LOH of this chromosome region has been described in several cancers including BRCA." (PMID 34001208, 2021). "Differential transcriptional expression of NEFM was profiled in tumor and adjacent non-malignant/normal tissues of multiple cancer types using Oncomine database." (PMID 34001208, 2021). "From Stage I, NEFM has been reported as a biomarker and as a methylated gene in cancer, however, it was not reported in LUAD." (PMID 24369052, 2013). "Here we identified specific CpG sites in L3MBTL1, NKX6-2, PREX1, TRAF7, PRDM14,and NEFM as primarily methylated in cancer specimens but not in other colonic lesions; these genes were also found to be implicated in many important pathways relevant to neoplastic transformation." (PMID 27688749, 2016).